NR4A1 (nuclear receptor subfamily 4 group A member 1)
Diseases named in the same sentence as NR4A1 in open-access papers (continued):
Sharing a sentence is not in itself a finding about the gene and the disease.
epilepsy (7 papers, 2016 to 2023). A brain disorder characterized by episodes of abnormally increased neuronal discharge resulting in transient episodes of sensory or motor neurological dysfunction, or psychic dysfunction. "Moreover, previous studies have identified that NR4A1 is an epilepsy-associated gene and its expression was up-regulated following seizure induction in both TLE patients and animal models." (PMID 32760244, 2020). "NR4A1 has been implicated in mediating synaptic plasticity, acquiring neuroprotection and neuronal differentiation during central nervous system development in epilepsy." (PMID 32760244, 2020). "In summary, to the best of our knowledge, this is the first attempt to link the NR4A1 methylation levels with multimodal neuroimaging data in epilepsy, which were also replicated in both left and right TLE subsets." (PMID 32760244, 2020). "This extends previous findings in a model of epilepsy in which NR4A1 expression protected hippocampal neurons from seizure-induced damage by rendering mitochondria more resistant to cellular stress and by reducing neuronal excitability." (PMID 29295823, 2018). "Currently, the molecular and cell biological mechanisms by which NR4A1 acts in epilepsy are largely unexplored." (PMID 27876882, 2016). "Here, we showed that NR4A1 protein was predominantly expressed in neurons and up-regulated in patients with epilepsy as well as pilocarpine-induced mouse epileptic models." (PMID 27876882, 2016). "To explore the role of NR4A1 in epilepsy, we inhibited the expression of NR4A1 by lentivirus transfection." (PMID 27876882, 2016). "More interestingly, it has been proved that NR4A1 knockdown by lentivirus transfection can prolong onset latency of epilepsy in mouse models, implicating that methylation of NR4A1 may play a pivotal role in seizure onset." (PMID 32760244, 2020). "The present study provided direct evidence that NR4A1 is up-regulated in patients with epilepsy and in mouse models and that NR4A1 knockdown alleviates seizure attacks, which may lead to a novel intervention strategy for human epilepsy." (PMID 27876882, 2016). "We found that NR4A1 was up-regulated in epilepsy, and NR4A1 knockdown alleviated seizure severity." (PMID 27876882, 2016). "Top upstream terms and network from the IPA analysis were HTT, NR4A1, CNTF, epilepsy, dyskinesia, synaptic depression, the organization of cells, and catalepsy." (PMID 36289639, 2022). "Furthermore, previous studies have identified that NR4A1 is an activity-inducible gene that regulates the density and distribution of spines and synapses which is related to excitatory synaptic strength, and mediates synaptic activity and neuroprotection in epilepsy, especially in temporal lobe." (PMID 32760244, 2020). "Notably, upregulation of NOVA1, neuroLSD1, and of the IEG proteins NR4A1, EGR1, and NPAS4 has been observed in patients with epilepsy and/or in epileptic mouse models, and their deregulation might contribute to DEE9 epileptic phenotype." (PMID 35613587, 2022). "NR4A1 inhibition may retard NR2B trafficking from the intracellular pool to the surface and also decreases their cell surface expression, which may suppress epilepsy." (PMID 27876882, 2016).
influenza infection (7 papers, 2012 to 2025). "Investigating Nr4a1-regulated immune responses to different pneumonic pathogens, such as S. pneumoniae, influenza, and Aspergillus, will help delineate the critical mechanisms underlying these phenotypes of host-pathogen interaction during pulmonary infection." (PMID 40114913, 2025). "This analysis revealed a significant enrichment of THBS1 and NR4A1 in the influenza samples, which are both genes that have been shown to be engaged in response to influenza-induced lung injury." (PMID 35233546, 2022). "Collectively, these results show that triggering of NR4A1 with Csn-B significantly contributes to protect mice from acute influenza infection." (PMID 29053748, 2017). "Ifi27l2a (also referred to as Isg12) is nuclear localized and regulates the function of the orphan nuclear receptor NR4A1 protein, especially in response to vascular inflammation, a likely byproduct of influenza infection." (PMID 22384400, 2012). "During influenza infection in the absence of the IFN-α/ß receptor, inflammatory and apoptotic responses may be initiated via induction of Ing1, Nr4a1, Polr2a, or Hoxa13." (PMID 38902760, 2024).
liver fibrosis (7 papers, 2021 to 2025). "Furthermore, nuclear receptor subfamily 4 group a member 1 (NR4a1)/Nur77 has been identified as key regulator of hepatic fibrosis and its suppression is heavily involved in the activation process of HSCs." (PMID 37572734, 2023). "Still, it remains unclear whether the role of NR4A1 in EMT in cancer is the same as in EMT in liver fibrosis and HSC activation." (PMID 35600274, 2022). "For example, numerous studies show that quercetin inhibits induced hepatic fibrosis and hepatic stellate cell activation by modulating many of the same responses observed for NR4A1 ligands, and the effects of quercetin on kidney fibrosis were also similar to those observed for NR4A1/ligands." (PMID 40871737, 2025). "Similar to NR4A1, SOX9 is also a transcription factor that plays vital roles in sexual differentiation, liver fibrosis and tissue repair." (PMID 36977670, 2023). "Therefore, NR4A1 might represent a promising antifibrotic target, but since the EMT mechanisms associated with liver fibrosis and those associated with cancer might be different, it remains unclear whether NR4A1 inhibits HSC activation and liver fibrosis by modulating the EMT." (PMID 35600274, 2022). "This study aimed to examine whether nuclear receptor 4a1 (NR4A1) is involved in inhibiting hepatic stellate cell (HSC) activation and liver fibrosis through the epithelial–mesenchymal transition (EMT)." (PMID 35600274, 2022). "This study aimed to examine whether NR4A1 is involved in inhibiting HSC activation and liver fibrosis through the EMT." (PMID 35600274, 2022). "NR4A1 inhibits TGF-β signaling, which can suppress experimental lung and liver fibrosis, but whether NR4A1 inhibits HSC activation and liver fibrosis through the EMT is unknown." (PMID 35600274, 2022). "Therefore, this study aimed to examine whether NR4A1 is involved in inhibiting HSC activation and liver fibrosis through the EMT." (PMID 35600274, 2022). "Hence, the findings suggest that NR4A1 plays an important role during HSC activation and that NR4A1 might be a promising therapeutic target for treating liver fibrosis." (PMID 35600274, 2022).
renal fibrosis (7 papers, 2021 to 2025). A final common manifestation of a wide variety of chronic kidney diseases characterized by glomerulosclerosis and tubulointerstitial fibrosis. "The same study revealed that Nr4a1 deficiency inhibits renal fibrosis and improves diabetic nephropathy in streptozotocin-induced diabetic nephropathy model mice." (PMID 38132237, 2023). "First, upregulation of renal tubular Nr4a1 in UUO mice was associated with the degree of renal fibrosis." (PMID 37161357, 2023). "On the other hand, Nr4a1 has also been shown to activate the p38 MAPK signalling pathway to promote renal fibrosis or to modulate the phenotypes of cardiac fibroblasts and macrophages, thereby facilitating angiotensin II‐induced cardiac fibrosis." (PMID 41332397, 2025). "Our results showed that the knockdown of NR4A1 can accelerate unilateral ureteral obstruction (UUO)-induced renal fibrosis in mice, and overexpression of NR4A1 can significantly reduce transforming growth factor-β1-induced (TGF-β1) fibrosis in HK-2 cells." (PMID 39736520, 2024). "Our results have demonstrated that both SPDEF and NR4A1 can negatively regulate the development of renal fibrosis." (PMID 39736520, 2024). "SPDEF is a transcription factor that can activate NR4A1 transcriptionally and subsequently contribute positively in the regulation of renal fibrosis." (PMID 39736520, 2024). "Our previous research has shown that NR4A1 expression is reduced in animal models of unilateral ureteral obstruction (UUO) induced renal fibrosis." (PMID 39736520, 2024). "Taken together, these results indicate that NR4A1 is downregulated in the cell model of renal fibrosis that is induced by TGF-β1 treatment, and NR4A1 overexpression can inhibit renal fibrosis." (PMID 39736520, 2024). "We studied the role of SPDEF and NR4A1 in renal fibrosis and their interaction by knocking down either of them." (PMID 39736520, 2024). "In summary, this study provided both in vivo and in vitro evidence supporting that induction of Nr4a1 promotes renal fibrosis potentially through the activation of p38 MAPK pathway." (PMID 37161357, 2023). "We then examined the expression of Nr4a1 in the kidney of a mouse model of UUO-induced renal fibrosis." (PMID 37161357, 2023). "The specific Nr4a1 agonist Cytosporone B (Csn-B) promoted renal fibrosis, and induced p38 MAPK phosphorylation." (PMID 37161357, 2023). "Collectively, these findings indicate that activation of Nr4a1 promotes the fibrotic change of renal tubular cells in renal fibrosis." (PMID 37161357, 2023). "We also determined the role of Nr4a1 in a cell model of renal fibrosis that is induced by TGF-β1 treatment." (PMID 37161357, 2023). "In diabetic nephropathy, Nr4a1 levels were positively related to renal fibrosis and glomerular apoptosis, and its induction contributed to high glucose-induced mitochondrial damage in human renal mesangial cells." (PMID 37161357, 2023). "Third, activation of Nr4a1 with the specific agonist Csn-B exacerbated renal fibrosis in UUO mice, and promoted TGF-β1-induced fibrotic changes in renal tubular cells." (PMID 37161357, 2023). "Second, activation of Nr4a1 with a specific agonist Csn-B exacerbated renal fibrosis in UUO mice, and promoted fibrotic changes in TGF-β1-treated renal tubular cells." (PMID 37161357, 2023). "The findings in the present study indicate that Nr4a1 promotes renal fibrosis potentially through activating p38 MAPK kinase." (PMID 37161357, 2023). "In the present study, we investigated the role and potential action mechanism of Nr4a1 in renal fibrosis by using kidney biopsies from UUO mouse model of renal fibrosis, and TGF-β1-treated renal tubular cells." (PMID 37161357, 2023). "Nr4a1 was observed to promote renal fibrosis in mice by activating tumor growth factor β-signaling and increasing collagen I/III/IV and MMP3." (PMID 38132237, 2023). "Taken together, these findings indicate that Nr4a1 promotes renal fibrosis at least partially through activating p38 MAPK." (PMID 37161357, 2023).
renal fibrosis (continued). "The reduction of NR4A1 expression is related to glucose metabolism disorders and renal fibrosis, and histone acetylation can help increase the expression of NR4A1 in patients with DKD." (PMID 35186975, 2021). "We also determined the role of NR4A1 in a cell model of renal fibrosis that is induced by TGF-β1." (PMID 39736520, 2024). "Knockdown of NR4A1 can significantly aggravate UUO-induced renal fibrosis to a great extent." (PMID 39736520, 2024). "Our findings suggest that SPDEF can improve renal fibrosis by activating NR4A1 transcriptionally." (PMID 39736520, 2024). "The results clarify that SPDEF can inhibit renal fibrosis by transcriptionally activating NR4A1." (PMID 39736520, 2024). "Collectively, these findings suggest that activation of Nr4a1-p38 MAPK promotes renal fibrosis." (PMID 37161357, 2023). "In addition, we provided further evidence that Nr4a1 promoted renal fibrosis potentially through activating p38 MAPK kinase." (PMID 37161357, 2023). "This suggests that Nr4a1 promotes renal fibrosis and glomerulosclerosis and may be a potential factor in the development of not only diabetic nephropathy but also age-dependent renal impairment." (PMID 38132237, 2023). "We suspected that LSD1 activated TGF-β signal pathway and directly induced renal fibrosis, which could be recruited by NR4A1 and formed a repressor complex to limit pro-fibrotic TGF-β effects." (PMID 34983623, 2022). "Further analysis showed that JMJD1A overexpression could accelerate the progression of AGEs-induced renal fibrosis by reducing the expression of NR4A1 in HK-2 cells." (PMID 35186975, 2021). "We hypothesized that SPDEF could inhibit renal fibrosis by activating NR4A1." (PMID 39736520, 2024). "Consequently, we speculate that increasing the expression of NR4A1 can effectively improve renal fibrosis." (PMID 39736520, 2024). "To further clarify the role of NR4A1 in renal fibrosis, we intervened UUO mice with the NR4A1 agonist Cytosporone B. HE staining results showed that UUO could induce extensive infiltration of inflammatory cells, resulting in renal tubular atrophy and deformation." (PMID 39736520, 2024). "We found that knocking down NR4A1 could aggravate UUO-induced renal fibrosis." (PMID 39736520, 2024). "Therefore, we speculate that SPDEF can inhibit renal fibrosis by transcriptionally activating NR4A1." (PMID 39736520, 2024). "However, the precise role of Nr4a1 in renal fibrosis remains largely unclear." (PMID 37161357, 2023). "We showed that Nr4a1 was upregulated in UUO mouse kidneys, and was positively correlated with the degree of renal fibrosis." (PMID 37161357, 2023). "The induction of Nr4a1 expression was accompanied with the activation of p38 MAPK phosphorylation in both in vivo and in vitro models of renal fibrosis." (PMID 37161357, 2023). "In renal fibrosis, the direct effect of LSD1 on TGF was greater than that of NR4A1 recruitment, resulting in LSD1 inducing renal fibrosis." (PMID 34983623, 2022). "Additionally, we found that overexpression of SPDEF can improve UUO-induced renal fibrosis in mice and TGF-β1-induced fibrosis in HK-2 by transcriptionally activating NR4A1." (PMID 39736520, 2024). "Previous research has shown that the SAM pointed domain containing Ets transformation-specific transcription factor (SPDEF) can activate NR4A1, but its mechanism of action in renal fibrosis is not yet clear." (PMID 39736520, 2024). "We further specifically knocked down or overexpressed NR4A1 in HK-2 cells with or without TGF-β1 to further confirm its role in renal fibrosis." (PMID 39736520, 2024). "We hypothesized that Nr4a1 may activate MAPK signaling pathway and therefore promote renal fibrosis." (PMID 37161357, 2023). "To verify our hypothesis, in the present study, we determined the role of Nr4a1 in renal fibrosis and the involvement of p38 MAPK in Nr4a1-mediated functions by using UUO mice and TGF-β1-treated HK-2 cells as in vivo and in vitro models of renal fibrosis." (PMID 37161357, 2023).
serous ovarian cancer (7 papers, 2016 to 2025). "Another literature also reported that high expression of NR4A1 in high grade serous ovarian cancers had worse prognosis." (PMID 32441484, 2020).
steatosis (7 papers, 2017 to 2024). Increased lipid within the cytoplasm of cells. "Genetic ablation of Nr4a1 ameliorated alcohol-induced hepatocyte vacuolization, fibrosis and steatosis in mice." (PMID 37161357, 2023). "Compared to the alcohol-treated WT mice, mice with genetic ablation of NR4A1 exhibited attenuation of hepatocyte vacuolation, fibrosis, steatosis, and caspase-9-related mitochondrial apoptosis induced by alcohol treatment." (PMID 31839999, 2019). "Moreover, NR4A1 knockout (NR4A1-KO) mice treated with alcohol for 16 weeks had less hepatocyte vacuolation, fibrosis, steatosis, and caspase-9-related mitochondrial apoptosis in comparison to the alcohol-treated WT." (PMID 32296016, 2020).
autoimmune disease (6 papers, 2015 to 2023). A disorder resulting from loss of function or tissue destruction of an organ or multiple organs, arising from humoral or cellular immune responses of the individual to their own tissue constituents. "The Nr4a orphan nuclear receptors, Nr4a1 (Nur77), Nr4a2 (Nurr1), and Nr4a3 (Nor1), are early‐immediate response genes that can be induced by a variety of physiological stimuli such as inflammation during experimental autoimmune disease models." (PMID 34358410, 2021).
bladder cancer (6 papers, 2015 to 2025). "In addition to their role of inhibiting proliferation in hematopoietic based malignancies Nr4a1 overexpression in UM-UC-3 bladder cancer cells decreased androgen stimulated proliferation, while Nr4a1 knockdown increased growth." (PMID 31683815, 2019). "Recently, some studies reported that nuclear receptors (NRs) such as Nur77 (NR4A1) and Nurr1 (NR4A2) were involved in bladder cancer progression." (PMID 25878394, 2015).
Cerebral ischemia (6 papers, 2001 to 2023). Restriction of arterial blood supply to the brain associated with insufficient oxygenation to support the metabolic requirements of the tissue. "The interaction between NR4A1 and NF-κB/p65 in microglia alleviates brain injury caused by cerebral ischemia, thus inhibiting neurogenic inflammation." (PMID 35681895, 2022). "Nuclear receptor subfamily 4 group A member 1 (NR4A1) inhibition protects against cerebral ischemia-reperfusion induced mitochondrial damage through upregulation expression of MFN2 and reversing MFN2-mediated mitophagy." (PMID 33609088, 2021).
cognitive deficits (6 papers, 2018 to 2025). "Among these genes were key transcriptional regulators (e.g., Ahr, Id2, Nr4a1, Nr4a3, Olig2, Zbed4), sustaining previous evidence that several severe cognitive disorders are associated with alterations in transcriptional regulatory activity." (PMID 37048129, 2023). "In human PFC tissues of men and women, high levels of the transcriptionally active NR4A1 correlated with measures of synaptic loss and cognitive impairment." (PMID 29295823, 2018). "Notably, genetic knockdown and chemical inhibition of Nr4a1 significantly ameliorated cognitive deficits as well as AD-like pathology in these subjects." (PMID 40468463, 2025).
diabetic nephropathy (6 papers, 2016 to 2025). "NR4A1 has been associated with promoting mitochondrial oxidative stress and has been implicated in the development of diabetic nephropathy." (PMID 39042632, 2024). "In consistency with our findings, Nr4a1 deletion was shown to attenuate high glucose-induced renal fibrotic lesions and collagen expression in diabetic nephropathy." (PMID 37161357, 2023). "NR4A1 knockdown suppresses high-glucose-induced mitochondrial fragmentation by modulating Miff and parkin transcription and improves diabetic nephropathy." (PMID 34067150, 2021).
fibrosis (6 papers, 2021 to 2025). the formation of excess fibrous connective tissue in an organ or tissue in a reparative or reactive process. "Another study found that NR4A1 agonists prevented NR4A1 inactivation and exerted antifibrotic effects in many organs of experimental fibrosis models." (PMID 37373277, 2023). "Indeed, reducing Tnfα signaling in nr4a1 mutants decreased cardiac fibrosis and improved cardiac regeneration." (PMID 40554763, 2025). "Fibrotic diseases appear to utilise this NR4A1-dependent mechanism to enable persistent TGF-β signaling and deregulated fibrosis and NR4A1 agonists inhibit laboratory-induced fibrosis of the skin, lung, liver, and kidney in mice." (PMID 36912952, 2023).
Hepatitis (6 papers, 2011 to 2025). Inflammation of the liver. "Activation of macrophage NR4A1 or SOX9 in Caspase 6-deficient livers aggravated liver inflammation." (PMID 36977670, 2023). "TokinolideB is a phthalide isolated from Angelica sinensis that binds NR4A1; like celastrol, tokinolide induces nuclear export of NR4A1 and exhibits anti-inflammatory activity in a mouse model of hepatitis." (PMID 40871737, 2025).